SELPLG (selectin P ligand)
Diseases named in the same sentence as SELPLG in open-access papers (continued):
Sharing a sentence is not in itself a finding about the gene and the disease.
infection (80 papers, 2007 to 2025). The state of being infected such as from the introduction of a foreign agent such as serum, vaccine, antigenic substance or organism. "SELPLG knock-out mice are susceptible to infection by streptococcus." (PMID 29297313, 2017). "Expression of the human SELPLG gene in transgenic mice can enhance virus replication and aggravate symptoms at the early stage of mouse-adapted EV71 strain infection." (PMID 37078358, 2023).
cancer (53 papers, 2014 to 2025). A tumor composed of atypical neoplastic, often pleomorphic cells that invade other tissues. "Other immune checkpoint ligands, such as NECTIN2, LGALS3, LGALS9, and SELPLG, were highly expressed in cancer cells or other infiltrating immune/stromal cells." (PMID 36529697, 2023). "Selectin P ligand gene (SELPLG) has been studied in several cancers." (PMID 35153625, 2022). "Recently, SELPLG has been demonstrated to act as an immune checkpoint regulator, which might be novel therapeutic target in cancer." (PMID 35153625, 2022). "Other immune checkpoint ligands or receptors, SELPLG, HAVCR2, LGALS3, and LGALS9, were highly expressed in cancer cells or other infiltrating cells." (PMID 36529697, 2023). "Gene Set Enrichment Analysis (GSEA) of the genes related to SELPLG in ALCL setting mainly detected genes involved in pathways and cellular functions specifically deregulated in cancer, including MYC and E2F target gene sets, apoptosis and programmed cell death." (PMID 34204843, 2021).
SELPLG also shares sentences with these, for which no sentence is quoted: psoriasis (24 papers); viral infection (18); HIV-1 infection (13); atopic dermatitis (11); lupus (11); Sepsis (10); Autoimmunity (9); leukemia (9); multiple myeloma (9); breast carcinoma (7); glioblastoma (7); cardiovascular diseases (6); Stroke (6); thrombosis (6); colitis (5); endothelial dysfunction (5); inflammation (5); asthma (4); autoimmune disease (4); Hypertension (4); lymphoma (4); systemic sclerosis (4); Thrombocytopenia (4); acute leukemia (3); allergic disease (3); Arterial thrombosis (3); cutaneous leishmaniasis (3); hypercoagulability (3); prostate tumor (3); pulmonary arterial hypertension (3).
A further 128 diseases each share a sentence with SELPLG in 3 papers or fewer.